ITGA3 (integrin subunit alpha 3)
Diseases named in the same sentence as ITGA3 in open-access papers (continued):
Sharing a sentence is not in itself a finding about the gene and the disease.
ovarian carcinoma (8 papers, 2018 to 2025). A malignant neoplasm originating from the surface ovarian epithelium. "Specifically, SPOCK2 promotes the invasion and migration of ovarian cancer cells, potentially through interactions with ITGA3 and the activation of FAK signaling, and is associated with a higher likelihood of metastasis." (PMID 41465326, 2025). "In our previous studies, ITGA3 assays have shown potential for the detection of bladder and ovarian cancers." (PMID 40287842, 2025). "These highlighted the integrins ITGA3/B4/B8 and indicated they may be important in promoting ovarian cancer progression." (PMID 32765584, 2020). "Hence, we surmised a critical role of alpha3beta4 heterodimer or distinctly independent functions of ITGB4 and ITGA3 played in ovarian cancer." (PMID 32765584, 2020). "Meanwhile, higher mRNA expression of ITGA3 and ITGB4/8 were significantly associated with poor PFS, lower mRNA expression of ITGA4/A6/A7/A10/AX and ITGB1 were significantly associated with poor PFS in ovarian cancer patients." (PMID 32765584, 2020). "Among all analyzed integrin genes, we found increased ITGA3/A5/A10/A2B and ITGB3/B4/B8 expressions were significantly associated with poor OS, while decreased ITGA6/A7/AE and ITGB7 expression were significantly associated with poor OS in ovarian cancer patients." (PMID 32765584, 2020).
head and neck cancer (7 papers, 2019 to 2024). A primary or metastatic malignant neoplasm affecting the head and neck. "miR-199 has been reported to regulate FN expression and to inhibit cell migration and invasion in head and neck cancer by regulating ITGA3." (PMID 31708963, 2019). "In head and neck cancer, knockdown of ITGA3 markedly suppressed cancer cell migration and invasion." (PMID 32232000, 2020).
head and neck squamous cell carcinoma (7 papers, 2019 to 2026). A squamous cell carcinoma that arises from any of the following anatomic sites: lip and oral cavity, nasal cavity, paranasal sinuses, pharynx, larynx, and salivary glands. "miRNAs have been shown to silence ITGA3 expression, and in turn inhibit cancer development, in head and neck squamous cell carcinoma." (PMID 31443155, 2019). "Additionally, immunohistochemistry experiments were conducted on Head and neck squamous cell carcinoma (HNSC) tissue samples to assess the impact of ITGA3 and others on patient prognosis." (PMID 41602372, 2026). "Interestingly, ITGA3 was also a component of the prognostic signature for head and neck squamous cell carcinoma, with a similar role like BAK1." (PMID 34335109, 2021). "In particular, for head and neck squamous cell carcinoma (HNSC), we not only identified the potential value of ITGA3/5/6 through bioinformatics analysis but also validated their role in patient prognosis with IHC, providing new insights into the mechanism of ITGA family genes in HNSC." (PMID 41602372, 2026). "Besides, miR-150-5p and − 3p targets ITGA3 (integrin alpha 3), ITGA6 (integrin alpha 6), and TNC (tenascin C) in head and neck squamous cell carcinoma." (PMID 37924077, 2023).
lung carcinoma (7 papers, 2021 to 2025). "Curcumin was reported to downregulate ITGA3 in lung cancer cells and cause inhibition of cell proliferation and invasion and induction of apoptosis." (PMID 34299042, 2021). "Knockout of ANXA1 expression inhibited the proliferation, migration, and invasion of lung carcinoma cells, while the expression level of ITGA3 can be used as a diagnostic and prognostic marker for several malignant tumors." (PMID 34350210, 2021). "Curcumin has been reported to significantly inhibited cell proliferation and invasion and induced death in lung cancer cells by downregulating ITGA3." (PMID 34366863, 2021). "Thus, CST6 and ITGA3 may be potential therapeutic targets for lung cancer." (PMID 34603393, 2021). "In addition, the CST6-related genes (ITGA3, LKL7, and KRT7 corresponding to TCGA lung cancer, SKCM, and renal cancer separately) were found to be associated with clinical outcomes." (PMID 34603393, 2021).
nasopharyngeal carcinoma (7 papers, 2017 to 2025). A carcinoma arising from the nasopharyngeal epithelium. "Increased expression of ITGA3 was noted in bladder, colorectal, pancreatic, prostate, nasopharyngeal carcinoma, and NSCLC cancers." (PMID 34299042, 2021). "In nasopharyngeal carcinoma, MicroRNA-101 inhibits invasion and angiogenesis through targeting ITGA3 and its systemic delivery inhibits lung metastasis." (PMID 28742860, 2017). "Additionally, miR-101 suppresses angiogenesis and metastasis of nasopharyngeal carcinoma cell through directly inhibiting ITGA3, and miR-203 abolished cervical cancer angiogenesis and growth of the tumor by targeting VEGF-A." (PMID 32123520, 2020).
congenital nephrotic syndrome (6 papers, 2014 to 2025). "Biallelic mutations in ITGA3 are linked to congenital nephrotic syndrome, interstitial lung disease, and epidermolysis bullosa." (PMID 41368354, 2025). "We describe two siblings carrying unreported missense mutations in the ITGA3 gene, which is responsible for Interstitial Lung disease, congenital Nephrotic syndrome and Epidermolysis Bullosa (ILNEB)." (PMID 27717396, 2016). "Recently, mutations in the human ITGA3 were shown to cause congenital nephrotic syndrome, epidermolysis bullosa and interstitial lung disease, otherwise termed NEP syndrome (Nephrotic syndrome, Epidermolysis bullosa and Pulmonary disease)." (PMID 24621570, 2014). "Homozygous mutations in ITGA3, the gene encoding integrin α3, in humans leads to congenital nephrotic syndrome, interstitial lung disease and epidermolysis bullosa with defects in the GBM." (PMID 25352829, 2014). "Homozygous mutations in ITGA3 in humans lead to congenital nephrotic syndrome." (PMID 25352829, 2014). "In addition, a mutation in ITGA3 causing a gain of glycosylation and preventing α3β1 dimer formation causes fatal interstitial lung disease and congenital nephrotic syndrome." (PMID 25352829, 2014). "Recently, however, ITGA3 homozygous mutations were reported in three patients with a multi-organ disorder comprised of congenital nephrotic syndrome, epidermolysis bullosa and interstitial lung disease, or NEP syndrome (Nephrotic syndrome, Epidermolysis bullosa and Pulmonary disease)." (PMID 24621570, 2014).
interstitial lung disease (6 papers, 2014 to 2025). A diverse group of lung diseases that affect the lung parenchyma. "Integrin α3 (ITGA3) gene mutations are associated with Interstitial Lung disease, Nephrotic syndrome and Epidermolysis bullosa (ILNEB syndrome)." (PMID 27717396, 2016). "More recently, a similar phenotype, consisting of interstitial lung disease and nephrotic syndrome was reported in child carrying a missense ITGA3 mutation that led to gain of glycosylation in the α3 subunit." (PMID 24621570, 2014).
colon cancer (5 papers, 2014 to 2025). "In colon cancer, ITGA3 seems to be generated reactive oxygen species, as a byproduct of integrin engagement, where the subsequent change in redox signaling may attenuate or even cause cellular migration." (PMID 40013338, 2025). "In gastric carcinomas, ITGA3 expression could facilitate the invasion and was considered as a key signature for colon cancer." (PMID 34335109, 2021). "On the other hand, lower expression of the ITGA3 gene (which encodes the α3 integrin subunit) has been correlated with metastasis and poor prognosis in CRC patients, and α3β1 expression was reported to be reduced during the transition of colon tumors from benign to malignant." (PMID 39941740, 2025). "To confirm the successful induction of the 6 model genes (SIRT3, PIK3CA, ITGA3, DAPK1, PAK1, and CASP3), we gathered a set of 39 colon cancer tissue samples." (PMID 38213716, 2024).
glioblastoma (5 papers, 2009 to 2026). The most malignant astrocytic tumor (WHO grade IV). "A study employing TCGA data, for example, found that high expression of the ITGA3 gene predicted a poor prognosis for glioblastoma." (PMID 35766985, 2022). "Integrin Alpha 3 (ITGA3) emerged as a conserved downstream effector of METTL7B, with progressive upregulation from minimally invasive to invasive LUAD and glioblastoma." (PMID 42122180, 2026).
glioma (5 papers, 2019 to 2025). A benign or malignant brain and spinal cord tumor that arises from glial cells (astrocytes, oligodendrocytes, ependymal cells). "Correlation analysis revealed that TSPAN4 was positively correlated with ITGB1, GDF15, ITGA3 and ITGA6, and negatively correlated with CHD7, ASPDH, TMEM8B and GHITM in glioma." (PMID 39723210, 2024).
metastatic tumors (5 papers, 2014 to 2025). "Consistently, lower ITGA3 expression has been correlated with metastasis and poor prognosis in CRC patients, and in many cases, metastatic tumors had lower α3 expression levels than their corresponding primary tumors." (PMID 39941740, 2025). "In the present study, even the direction of the mRNA expression was similar for ITGA3, we observed significant decrease only for the ITGA2 gene in the metastatic tumors." (PMID 36091936, 2022).
non-small cell lung carcinoma (5 papers, 2021 to 2022). A group of at least three distinct histological types of lung cancer, including non-small cell squamous cell carcinoma, adenocarcinoma, and large cell carcinoma. "Moreover, a recent study revealed the important prognostic role of ITGA3 in patients with non-small cell lung cancer." (PMID 34603393, 2021).
pancreatic ductal adenocarcinoma (5 papers, 2018 to 2026). An infiltrating adenocarcinoma that arises from the epithelial cells of the pancreas. "Our previous study of pancreatic ductal adenocarcinoma (PDAC) cells showed that aberrant expression of ITGA3 and ITGB1 (genes for two integrins that form homodimers) was significantly associated with poor prognosis of patients with PDAC." (PMID 34199886, 2021).
papillary thyroid carcinoma (5 papers, 2019 to 2025). "ITGA3 is an independent risk factor of papillary thyroid cancer recurrence." (PMID 35174063, 2021). "The expression level of ITGA3 is much higher in PTC tissues than that in normal thyroid tissues in 5 of the subsets, except the follicular variant papillary carcinoma subset." (PMID 35174063, 2021). "In the Oncomine database, there are 3 distinct datasets involving the expression of ITGA3 in papillary thyroid carcinoma and normal thyroid tissue, which contains 6 subsets and 74 tumor samples." (PMID 35174063, 2021). "In the clinical case, expression of miR‐524‐5p, FOXE1, and ITGA3 were significantly correlated with papillary thyroid cancer development and progression." (PMID 30941771, 2019). "Studies have examined the role of integrin α3 (ITGA3) in papillary thyroid carcinoma (PTC)." (PMID 40138447, 2025). "Mechanistically, it has been reported that miRNA-524-5p inhibits the progression of papillary thyroid carcinoma cells by targeting FOXE1 and ITGA3 in cell autophagy and cycling pathways." (PMID 35488119, 2022). "MiR-524-5p, a downregulated miRNA in papillary thyroid carcinoma, was shown to promote autophagy and inhibit cell viability, invasion, migration and apoptosis by targeting ITGA3 and FOXE1 in papillary thyroid cancer." (PMID 33390839, 2021). "The expression of miR‐524‐5p was decreased in the papillary thyroid cancer tissues and cell lines, while forkhead box E1 (FOXE1) and ITGA3 were increased." (PMID 30941771, 2019). "miR‐524‐5p could inhibit papillary thyroid cancer cell viability, migration, invasion, and apoptosis through targeting FOXE1 and ITGA3." (PMID 30941771, 2019).
triple-negative breast carcinoma (5 papers, 2019 to 2025). An invasive breast carcinoma which is negative for expression of estrogen receptor (ER), progesterone receptor (PR), and human epidermal growth factor receptor 2 (HER2). "Previously, we used RNA interference (RNAi) technology to suppress the expression of the ITGA3 gene (encoding the α3 subunit) in the triple-negative breast cancer cell line, MDA-MB-231, thereby generating variants of this line with reduced expression of integrin α3β1." (PMID 34270616, 2021). "The expression of ITGA3 in triple-negative breast cancer was significantly lower than that in the luminal and HER2-positive subtypes." (PMID 34094951, 2021). "In triple-negative breast cancer (TNBC) cases, ITGA3 expression was significantly lower than in the Luminal and HER2-positive subtypes, aligning with data from CPTAC samples." (PMID 40181838, 2025).
benign prostate hyperplasia (4 papers, 2013 to 2024). "In other fluids, ITGA3 was more enriched in exosomes collected from urine of metastatic PCa patients compared to non-metastatic patients and benign prostatic hyperplasia." (PMID 32824235, 2020). "Finally, ITGA3 and ITGB1 were more abundant in urine exosomes of metastatic patients (p<0.05), compared to benign prostate hyperplasia or PCa." (PMID 24371517, 2013). "More importantly, as a proof of concept, we have identified the proteins ITGA3 and ITGB1 to be significantly more abundant in urine of mPCa compared to benign prostate hyperplasia (BPH) and PCa patients." (PMID 24371517, 2013).
cervical carcinoma (4 papers, 2020 to 2025). A carcinoma arising from either the exocervical squamous epithelium or the endocervical glandular epithelium. "MUC1 was overexpressed in CSCC, activating the phosphorylation of ERK, which enhanced the expression of ITGA2 and ITGA3, thereby promoting the malignant progression of cervical cancer cells." (PMID 38702644, 2024). "Transwell migration and invasion assays showed that reducing ITGA2 and ITGA3 expression significantly decreased the migration and invasion of cervical cancer cells." (PMID 38702644, 2024). "In the present study, we found that the mRNA level of ITGA2 and ITGA3 were increased in cervical cancer patients via the TCGA database." (PMID 38702644, 2024). "Further knockdown of ITGA2 and ITGA3 significantly inhibited the tumorigenesis of cervical cancer cells." (PMID 38702644, 2024). "We treated cervical cancer cells with a new inhibitor of ERK (MK-8353) and found that the expression of ITGA2 and ITGA3 was significantly reduced." (PMID 38702644, 2024). "MUC1 could upregulate ITGA2 and ITGA3 expression via ERK phosphorylation, promoting the proliferation and metastasis of cervical cancer cells." (PMID 38702644, 2024).
epidermolysis bullosa (4 papers, 2014 to 2025). Epidermolysis bullosa (EB) is a group of genetic skin diseases that cause the skin to blister very easily. "In particular, the ITGA3 gene has been recently associated to a generalised JEB with respiratory and renal involvement (JEB-RR) or Congenital Interstitial Lung disease, Nephrotic syndrome and Epidermolysis bullosa (ILNEB, OMIM#614748)." (PMID 27717396, 2016).
gastric cancer (4 papers, 2021 to 2024). A primary or metastatic malignant neoplasm involving the stomach. "Non coding RNAs such as circRNA ITGA3 regulated the invasion and migration of gastric cancer, and their efficacy in the prevention and treatment of gastric cancer in matrine." (PMID 39314750, 2024). "Studies have shown that DNA methylation plays a key role in the development of early gastric cancer, and ITGA3 methylation is related to mixed gastric cancer." (PMID 34094951, 2021).
pancreatic adenocarcinoma (4 papers, 2012 to 2022). "The ITGA3 gene expression data were extracted from The Cancer Genome Atlas (TCGA) pancreatic adenocarcinoma (PAAD) cohort and 14 Gene Expression Omnibus microarray datasets." (PMID 36561844, 2022).
esophageal cancer (3 papers, 2018 to 2021). A primary or metastatic malignant neoplasm involving the esophagus. "In the Oncomine database, ITGA3 gene was highly expressed in head and neck, kidney, bladder, pancreatic, and esophageal cancers and so on, with 26 datasets involved in the group." (PMID 35174063, 2021). "Furthermore, DUXAP8 is positively related to MAGEA4, GABRA3 expression, and negatively related to INPP5A, TIMP4 expression in esophageal cancer; LINC00460 is positively related to ITGA3, LAMC2 expression, and negatively related to FOXO4, KLF15 expression in esophageal cancer." (PMID 29926523, 2018).
hepatocellular carcinoma (3 papers, 2013 to 2025). A malignant tumor that arises from hepatocytes. "ITGA3 was reported previously to be an essential host factor for nHEV particle entry into PLC/PRF/5 hepatoma cells." (PMID 40571699, 2025). "To our surprise, we were barely able to detect ITGA3 in other, highly HEV-permissive hepatoma cell lines." (PMID 40571699, 2025).
nephrotic syndrome (3 papers, 2014 to 2025). A collection of symptoms that include severe edema, proteinuria, and hypoalbuminemia; it is indicative of renal dysfunction. "Sanger sequencing and WES have been used to identify mutations of ITGA3 in patients with nephrotic syndrome or ILNEB syndrome." (PMID 41368354, 2025). "Mutations in ITGA3 compromise adhesion and trigger foot process detachment, leading to nephrotic syndrome and GBM disorganization." (PMID 41368354, 2025). "From a practical point of view, ITGA3 may be not only exclusively included in congenital nephrotic syndrome genes screen but also in a large survey of CAKUT-causing mutations." (PMID 24621570, 2014).
Stroke (3 papers, 2017 to 2024). Sudden impairment of blood flow to a part of the brain due to occlusion or rupture of an artery to the brain. "Itga3 as a proposed receptor for Netrin-1 might facilitate and enhance cell-contact-dependent axon guidance within the stroke-denervated hemicord." (PMID 30962276, 2019). "Collectively these data suggest that AKAP7 expression is a marker of ITGA3-mediated lymphocyte adhesiveness and is likely elevated in patients who later develop post-stroke BBB disruption as a result of the presence of an invasive lymphocyte population in peripheral blood." (PMID 28446746, 2017). "Thus, our results suggest that AKAP7 and ITGA3 are molecules which could potentially be targeted therapeutically to limit lymphocyte-mediated post-stroke injury exacerbation." (PMID 28446746, 2017).
cutaneous melanoma (2 papers, 2021 to 2024). A primary melanoma arising from atypical melanocytes in the skin. "While this protective mechanism and how ITGA3 acts as a braker for invasiveness require further studies, the paper highlights integrins playing essential roles during the dedifferentiation process in primary cutaneous melanoma." (PMID 38319712, 2024).
diabetic nephropathy (2 papers, 2024 to 2025). "Single-nucleotide polymorphisms (SNPs) in ITGA3 may influence susceptibility to kidney diseases like FSGS or diabetic nephropathy, though research is ongoing." (PMID 41368354, 2025). "Interestingly, downregulated ITGA3 expression was also reported in the early stages of human and experimental diabetic nephropathy." (PMID 38891801, 2024).
Hepatic fibrosis (2 papers, 2022 to 2025). The presence of excessive fibrous connective tissue in the liver. "Furthermore, the protein levels of EpCAM and ITGA3 in liver‐derived EVs were positively correlated to the severity of hepatic fibrosis and were increasingly associated with the progression of MASLD." (PMID 40313415, 2025).
liver cancer (2 papers, 2020 to 2026). An epithelial or non-epithelial malignant neoplasm that arises from the liver. "Upregulated ITGA3 has been linked with a progression of renal failure and pathological features of liver cancer." (PMID 32612536, 2020).
lymphoma (2 papers, 2021 to 2025). A malignant (clonal) proliferation of B- lymphocytes or T- lymphocytes which involves the lymph nodes, bone marrow and/or extranodal sites. "Interestingly, B cells and lymphomas did not express ITGA3‐bound CD151 compared to T cells that expressed two different populations of integrin‐bound and integrin‐free CD151." (PMID 40464949, 2025).